CRP (C-reactive protein)
Diseases named in the same sentence as CRP in open-access papers (continued):
Sharing a sentence is not in itself a finding about the gene and the disease.
pancreatitis (continued). "The clinical criteria pain could be replaced by other indicators of the unfolding inflammation, such as CRP, especially if it is accompanied with clinical findings suggesting pancreatitis." (PMID 36449249, 2023). "Thus, further longitudinal evaluation of the serum calprotectin-to-S100A12 ratio in larger cohorts of dogs with different presentations and severities of pancreatitis and in comparison to serum CRP concentrations is warranted." (PMID 37505833, 2023). "A negative association with POPF was seen for history of pancreatitis, low postoperative CRP, and weight loss." (PMID 34370113, 2022). "Moreover, CRP levels were also significantly higher among patients with severe pancreatitis (P-value = 0.020)." (PMID 36340538, 2022). "Furthermore, patients with severe pancreatitis had significantly higher means of white blood cells, urea, lactate dehydrogenase, aspartate transferase, blood glucose, and peak CRP (P-value < 0.05)." (PMID 36340538, 2022). "Hence, it is widely accepted that elevated level of CRP as a surrogate marker of severe pancreatitis and higher mortality." (PMID 33564553, 2021). "Serum CRP concentration is affected by a wide variety of conditions of different organs, whereas serum cPLI is specific for acinar cell damage and pancreatitis." (PMID 34250650, 2021). "A previous retrospective study with ten PAP patients has implied that high preoperative CRP levels could indicate more severe pancreatitis which might lead to total pancreatectomy." (PMID 34944909, 2021). "However, it is not uncommon for dogs to have at least 1 other concurrent condition or systemic complication in addition to moderate or severe pancreatitis, making it difficult to determine a correlation between CRP and improving or worsening pancreatitis." (PMID 34250650, 2021). "However, CRP must be measured more than 48 h after the beginning of clinical symptoms because the peak CRP level appears 24 to 48 ho after the onset of pancreatitis." (PMID 34579512, 2021). "At 48 hours, raised levels of CRP may be due to non-pancreatitis-related complications like cholecystitis, cholangitis, urinary tract infection, or nosocomial respiratory tract infection." (PMID 34900460, 2021). "C-reactive protein (CRP) was also shown to be useful in predicting the course of pancreatitis." (PMID 33564553, 2021). "CRP is synthesised in the liver after induction of interleukin-1 (IL-1) and interleukin-6 (IL-6) and it has been used to assess the severity of inflammatory response, The use of CRP in pancreatitis as a marker to assess the course of the disease had been there since the 1980s." (PMID 33564553, 2021). "Therefore, clinical trials investigating the safety and efficacy of CRP apheresis during pancreatitis and after coronary bypass surgery are ongoing (CAPRI1-study DRKS00014265; CABY1-study DRKS00013012)." (PMID 32932587, 2020). "CRP was 250 mg/L and pancreatic enzymes were elevated, suggesting pancreatitis." (PMID 32961994, 2020). "However, as far as we know, there is still no published study on the success of BISAP in combination with CRP regarding predicting the severity of pancreatitis." (PMID 31114724, 2019). "Our findings may be explained by CRP being a late markerin the laboratory monitoring of post-ERCP pancreatitis." (PMID 18670651, 2008). "Age, gender, cause of pancreatitis and C-reactive protein levels at 48 h were not significantly different between the two groups." (PMID 16137360, 2005). "However, previous studies support the prognostic value of cPL and CRP in pancreatitis." (PMID 40524736, 2025). "Thus, serum amylase activity along with CRP on POD2–3 can be helpful in the diagnosis of significant pancreatitis when carefully evaluated within a clinical context that takes into account symptoms like fever, nausea, vomiting, tachycardia, tachypnea, hypotension, and oliguria." (PMID 37308735, 2023).
pancreatitis (continued). "In addition, a meta-analysis of 31 canine, rodent, and human studies provides evidence indicating the beneficial effect of corticosteroids on circulating CRP levels and hospitalization, whose administration during a pancreatitis episode is sometimes controversial." (PMID 36290272, 2022). "ROC analysis was used to calculate the appropriate sensitivity, specificity, positive predictive value, negative predictive value, positive likelihood ratio, negative likelihood ratio and diagnostic accuracy of CRP/Albumin ratio in determining severe pancreatitis against a CT severity score." (PMID 36268355, 2022). "In a recent study, it was suggested that serum canine pancreatic lipase immunoreactivity (cPLI) which is the most commonly used marker for pancreatitis confirmation, together with CRP could be used as objective biomarkers for clinical improvement in hospitalized dogs." (PMID 36290272, 2022). "Similarly, in another guideline, the original literature supporting the evidence for CRP is a review in which the author refers to the use of the Atlanta classification (1992) in a meta-analysis of the accuracy of CRP in the diagnosis of severe pancreatitis." (PMID 33419464, 2021). "Following pancreatectomy, elevation of CRP levels in the early period and persistently elevated levels may occur due to pancreatitis, tissue ischemia, tissue necrosis due to anastomotic leakage, wound site infection (developing due to ischemia at the wound site), and bacterial infection." (PMID 29619047, 2018). "First, during the acute phase of pancreatitis, ALB production is frequently suppressed as the liver shifts to synthesize acute-phase proteins (e.g., C-reactive protein (CRP)) due to a systemic inflammatory response driven by cytokines (e.g., IL-6)." (PMID 40308642, 2025). "In the comparison of clinical data and complications in patients with pancreatitis, fasting days, BISAP score, patient’s first bowel movement time, NLR, Glu, CRP, ALB, and BUN all have an impact on the occurrence of complications in patients with pancreatitis." (PMID 39331915, 2024). "The Prediction Pancreatitis Severity (PPS) Score I uses five criteria for admission (age, BMI, CR, gender, and WBC) but requires a complicated calculation; the PPS II added CRP at 48 hrs to the calculation." (PMID 37954725, 2023). "Thus, serum amylase together with CRP and careful interpretation within a clinical context regarding symptoms such as fever, nausea, vomiting, tachycardia, tachypnoea, hypotension, and oliguria suggesting pancreatitis should be sufficient in diagnosing the most important POH." (PMID 36449249, 2023). "In this study, a logistic model for predicting severe pancreatitis was constructed from three inflammatory indices (HBP, CRP, and PCT) in 212 patients." (PMID 37296194, 2023). "Serum parameters, including serum amylase, cholesterol and C-reactive protein (CRP), are reported as potential biomarkers for pancreatitis." (PMID 36999014, 2023). "While CRP is increased in patients with PDAC compared with controls, it is also elevated in patients with moderate and severe pancreatitis." (PMID 36969742, 2022). "The early improvement in CRP is consistent with it being a protein released from the liver, and also by adipocytes, which generate NEFA during pancreatitis." (PMID 31963691, 2020). "The combination of CRP values with BISAP values had high sensitivity and specificity for predicting the severity of pancreatitis." (PMID 31114724, 2019). "Besides SIG, CRP, PNI, and WBC all have been reported to be related to the severity of pancreatitis." (PMID 40672827, 2025). "This strong enhancement correlated with CRP and CAR during the following course of pancreatitis." (PMID 39964633, 2025). "In relatively mild pancreatitis cases, the mean CRP level did not significantly (p > 0.05) differ in the control group." (PMID 40524736, 2025).
pancreatitis (continued). "The CRP/albumin ratio integrates two laboratory parameters that reflect the inflammatory response and negative protein balance in pancreatitis." (PMID 38283464, 2023). "With the progressing pancreatitis, PCT and CRP also increased." (PMID 38093973, 2023). "The CRP concentration was neither significantly higher in dogs with an US diagnosis of pancreatitis nor did CRP differ significantly between presence or absence of the four recorded US variables." (PMID 36468410, 2023). "The CRP concentrations also did not correlate significantly with an US diagnosis of pancreatitis (n = 32 dogs)." (PMID 36468410, 2023). "A median CRP of 112 mg/L was consistent with very high CRP depicted in all the series of MIS-C with or without pancreatitis." (PMID 34927163, 2022). "Against this background, peak serum CRP levels during the early period after SPKT might be useful to assess the degree and severity of IRI, specifically postreperfusion pancreatitis in our patients." (PMID 35743457, 2022). "In addition, previous studies have found that the SII has a higher prognostic accuracy than other traditional inflammatory factors (such as C-reactive protein (CRP), serum albumin, and triglyceride levels) in patients with severe pancreatitis." (PMID 36294194, 2022). "CRP/albumin ratio has higher sensitivity and negative predictive value to predict severe pancreatitis than CRP alone and hence give additional advantage as a prognostic marker, although Delong's test to compare AUROC was indifferent (P-value: 0.22)." (PMID 36268355, 2022). "Serum CRP concentrations correlated with clinical severity in all dogs with pancreatitis, but not in surviving dogs with pancreatitis." (PMID 34250650, 2021). "According to the revised Atlanta criteria, 165 cases (79.7%) were mild, 30 (14.4%) were moderate, and 5.8 (12%) were severe pancreatitis, and when these three groups were compared, we found a significant difference between the mean hospital stay time, BISAP scores, and CRP values (p <0.001)." (PMID 31114724, 2019). "Compared with patients without fatty liver, the severity of pancreatitis and levels of serum C-reactive protein were higher in fatty liver patients." (PMID 28536603, 2017). "Severe post-procedural abdominal pain with/without pancreatitis, signs of peritonitis, fever and increased levels of CRP and white blood cells were accepted as suspected perforation." (PMID 25426633, 2014). "An additional value of the assessment of CRP is the distinction between necrotizing and edematous pancreatitis regardless of the severity of disease." (PMID 23342125, 2013). "This case report is limited by the absence of inflammatory markers, such as C-reactive protein, at initial presentation, which may have aided in assessing the severity of pancreatitis." (PMID 40821697, 2025). "However, we observed neither clinical signs nor symptoms of pancreatitis, nor did we detect any inflammatory markers, e.g., elevated C-reactive protein." (PMID 41390895, 2025). "It is also possible that some patients within the “normal response” group had elevated CRP measurements for other reasons in the absence of infections, including trauma, recent surgery, and inflammatory conditions such as pancreatitis; although these are likely to account for a minority of episodes." (PMID 38599549, 2024). "In the first one, the values of CRP and ferritin, together with the other three APPs that are include in our profiles (i.e., Hp, albumin and PON-1) in dogs with pyometra were compared with healthy dogs and with dogs suffering from another inflammatory condition such as pancreatitis." (PMID 37344860, 2023). "Serum CRP concentration might be more useful in dogs with pancreatitis but without concurrent conditions or complications." (PMID 34250650, 2021).
pancreatitis (continued). "On admission, mean plasma levels of neither IL-8 nor TNF-α and CRP showed any significant difference between two groups but on day 2, significantly higher values for IL-8 were observed on the group of patients with severe pancreatitis." (PMID 20130823, 2009). "In our study, C-reactive protein and procalcitonin levels were not routinely monitored in some patients, and since there is no clear evidence in the literature regarding the relationship between these parameters and pancreatitis, these markers were not our focus." (PMID 40429414, 2025). "Therefore, since these parameters used in daily practice are increased in many diseases, their use may not be safe in predicting severe pancreatitis, just like CRP, as seen in our results." (PMID 38905397, 2024). "The Prediction Acute Pancreatitis Severity (PAPS) Score I, which excludes CRP, is calculated using the following regression equation: PAPS Score I = 1.237 + 0.144 × nonA-nonB etiology (0 = no, 1 = yes) + 0.001 × WBC1 + 0.027 × VAS0." (PMID 40002586, 2025). "In our study, the median change in Spec cPL and CRP from the day of MSC administration to two days later was not statistically different from the change in Spec cPL and CRP from day of pancreatitis diagnosis to two days later in the control population." (PMID 39409854, 2024). "Levels of serum amylase, lipase, C-reactive protein (CRP), urea, creatinine and calcium were analysed and not found to be statistically significant in means of mortality or severity of pancreatitis." (PMID 36742275, 2023). "Since CRP, PCT and IL-6 had been demonstrated to be elevated by various conditions without infection, i.e., trauma, surgery, burn, pancreatitis, we decided to analyze the subgroup populations." (PMID 27287669, 2016). "C-reactive protein did not correlate to NPP7 activity (data not shown) and there was no indication that inclusion of some patients with pancreatitis or cholangitis related to stone in ductus choledochus significantly influenced group comparisons." (PMID 25100243, 2014). "However, as nonspecific acute-phase reactants, CRP and PCT levels may also rise in sterile inflammatory conditions such as pancreatitis, major surgery, or cardiopulmonary resuscitation, limiting their specificity." (PMID 39867344, 2024).
Hepatic steatosis (128 papers, 2006 to 2026). Steatosis is a term used to denote lipid accumulation within hepatocytes. "In CRP, the risk of developing hepatic steatosis increased monotonically with increasing CRP levels, using <1.0 as a reference." (PMID 38979415, 2024). "The present study showed that hs-CRP values were associated with biopsy-proven liver steatosis, NASH, and fibrosis." (PMID 37029427, 2023). "In multivariate logistic regression analysis, including age, BMI, duration of disease, AST, GGT, use of steroids, use of nicotine, and CRP, disease duration was the only variable that was independently associated with hepatic steatosis." (PMID 35566749, 2022). "It is documented that elevated hs-CRP values even within the normal range are associated with higher risk of NAFLD development particularly in the presence of hepatic steatosis." (PMID 33919641, 2021). "Although the studies were not uniform in design, all reported that weight loss, improved glycemic control, and hepatic steatosis were associated with varying degrees with serum C-reactive protein (CRP) reduction (Kuryłowicz and Koźniewski, 2020)." (PMID 33519369, 2020). "Previous study has showed that the PPP1RB polymorphisms were associated with hepatic steatosis and plasma serum CRP traits." (PMID 29681992, 2018). "An association between hepatic steatosis and elevation of CRP, a protein produced predominately by the liver under conditions of inflammation found by Ndumele and colleagues." (PMID 27547235, 2016). "For the atherosclerotic and inflammatory risk profiles, we found that Framingham risk, CRP values and lymphocytes counts decreased with steatohepatitis, fatty liver only and the normal pattern." (PMID 16707022, 2006). "Many studies have confirmed the association between high CRP and liver steatosis." (PMID 41480537, 2025). "Therefore, this suggests that alcohol abuse may cause fatty liver and induce high serum CRP levels, indicating that CRP may be qualified as a unique biomarker of AFL." (PMID 21806828, 2011). "Hepatic steatosis is closely associated with chronic low-grade inflammation, characterized by elevated pro-inflammatory cytokines such as TNF-α, IL-6, and C-reactive protein." (PMID 40502403, 2025). "The conclusion was that bariatric surgery led to a significant decrease in CRP values and hepatic steatosis and that CRP values before surgery cannot predict the success of weight loss and the liver status after RYGB." (PMID 40435018, 2025). "Specifically, it improves levels of transaminases, fasting glycemia, the lipid profile, the high-sensitivity C-reactive protein, and the degree of liver steatosis." (PMID 40142198, 2025). "Lastly, systemic biomarkers of inflammation, including C-reactive protein levels, positively correlate with the severity of hepatic steatosis and fibrosis." (PMID 38879469, 2024). "The degree of adiponectin increase indeed correlated with weight change, as well as with improvement of CMH markers, including IR, lipids, hs-CRP and hepatic steatosis." (PMID 38730247, 2024). "In Chinese obese patients, high serum CRP levels were associated with an increased risk of MAFLD and were positively related to the severity of hepatic steatosis and fibrosis." (PMID 38491346, 2024). "CRP: C-reactive protein; MAFLD: Metabolic dysfunction associated fatty liver disease; MR: mendelian randomization." (PMID 39376593, 2024). "In our studied population, hs-CRP values showed an acceptable specificity towards liver steatosis or fibrosis." (PMID 37029427, 2023). "Previously, we reported that feeding soy protein with high or low (negligible) isoflavone reduces liver steatosis in obese Zucker rats, and the reduced steatosis is accompanied by decreased serum C-reactive protein levels." (PMID 38075211, 2023). "The nomenclature of MASLD emphasizes the central role of metabolic dysfunction in the pathogenesis of fatty liver, in which CRP affects the regulation of fat metabolism by leptin, forming the first hit." (PMID 37893085, 2023).